GDF15 (growth differentiation factor 15)
Diseases named in the same sentence as GDF15 in open-access papers (continued):
Sharing a sentence is not in itself a finding about the gene and the disease.
metabolic syndrome (36 papers, 2017 to 2025). A cluster of metabolic risk factors for CARDIOVASCULAR DISEASES and TYPE 2 DIABETES MELLITUS. "HALS is usually associated with dyslipidemia, but there was only a weak correlation between lipid and GDF15 levels among our patients, which disappeared after age adjustment except for LDL, PUFA, and MUFA." (PMID 35160008, 2022). "Significant associations were also observed between GDF15 and components of metabolic syndrome, specifically, levels of serum triglycerides (beta = 0.13, p-value = 2.4 × 10–22), fasting insulin (beta = 0.10, p-value = 1.2 × 10–13) and waist-to-hip ratio (WHR) (beta = 0.049, p-value = 7.0 × 10–10)." (PMID 35916366, 2022). "In humans, the hyperglycemia-related compound of the metabolic syndrome complex is related to elevated serum GDF15 levels." (PMID 40820083, 2025). "The authors also highlighted a link between increased GDF15 serum levels and dyslipidemia patterns, thus corroborating our findings regarding the association with triglycerides." (PMID 40650260, 2025). "These mechanistic insights establish a robust molecular foundation for developing GDF15-targeted therapies, with particular translational potential in metabolic syndrome-related pathologies and other diseases." (PMID 40673270, 2025). "Elevated GDF-15 levels have previously been related to hs-CRP in individuals ≥ 65 years of age with metabolic syndrome." (PMID 39000435, 2024). "Adjusted odds ratios for the components of metabolic syndrome according to adiponectin and GDF-15/adiponectin." (PMID 37152921, 2023). "Biomarkers have been suggested in some instances of AF, e.g., in patients with metabolic syndrome having AF, for which Gal-3 and growth/differentiation factor-15 (GDF-15) were suggested to be predictors of AF recurrence." (PMID 37849915, 2023). "This study aimed to evaluate the roles of GDF-15, adiponectin, and GDF-15/adiponectin ratio (G/A ratio) as biomarkers for detecting metabolic syndrome (MS)." (PMID 37152921, 2023). "In line with its initial name macrophage inhibitory cytokine, GDF-15 thus limits pathological adipose tissue inflammation, reverts insulin resistance and ameliorates metabolic syndrome by metabolically modulating macrophage function." (PMID 32508832, 2020). "There is evidence of increased GDF15 secretion by Schwann cells in nerve injury, and increased GDF15 levels have been found in patients with diabetic neuropathy, mainly with more pronounced manifestations of metabolic syndrome." (PMID 39156689, 2024). "Moreover, increased levels of GDF-15 have been reported in individuals with the metabolic syndrome, which correlated to high-sensitivity C-reactive protein (hs-CRP) and elevated glucose levels." (PMID 39000435, 2024). "Odds ratios for metabolic syndrome according to GDF-15, adiponectin, and GDF-15/adiponectin." (PMID 37152921, 2023). "In this article, we review current knowledge on GDF15 and its involvement in metabolic syndrome." (PMID 36992609, 2023). "GDF15 is expected to be a candidate drug for the treatment of metabolic syndrome in the future." (PMID 32965044, 2021). "Furthermore, GDF‐15 is also a marker of inflammation and metabolic syndrome frequently seen in patients with HF." (PMID 32589369, 2020). "In parallel, we analyzed plasma GDF15 levels in 18 male PLWH on stable, long‐term antiretroviral therapy and 13 HIV‐negative men (6 healthy controls and 7 with metabolic syndrome)." (PMID 35510313, 2022). "Age, homeostatic model assessment of insulin resistance 1 (HOMA1-IR), HALS, dyslipidemia, C-reactive protein, and CVR estimated with the Framingham score correlated with GDF15 levels." (PMID 35160008, 2022). "Induction of metabolic syndrome in GDF-15 knock-out mice revealed that IL-4, IL-13, or rosiglitazone-based treatments depend on the JAK/STAT6- or PPARγ-dependent upregulation of GDF-15 in macrophages." (PMID 32508832, 2020).
metabolic syndrome (continued). "Their respective GDF15 levels were 3.06 [2.69–3.46] and 2.82 [2.54–3.13] log10 pg/mL for those with or without metabolic syndrome (p = 0.044)." (PMID 35160008, 2022).
endothelial dysfunction (35 papers, 2015 to 2026). In vascular diseases, endothelial dysfunction is a systemic pathological state of the endothelium (the inner lining of blood vessels) and can be broadly defined as an imbalance between vasodilating and vasoconstricting substances produced by (or acting on) the endothelium. "Age is one of the strongest determinants of GDF-15 serum levels, and correlates with endothelial dysfunction, and chronic comorbidities commonly associated with aging." (PMID 41597417, 2026). "Elevated GDF-15 levels correlate with cardiometabolic risk, inflammation, and endothelial dysfunction and are linked to vascular disease." (PMID 41597417, 2026). "In accordance with other patient populations, suPAR and GDF-15 emerge as markers of endothelial dysfunction, characterizing high-risk in endothelial injury syndromes, and, in particular, CRS." (PMID 39456810, 2024). "Given the shared involvement of ET-1 and GDF-15 in fibrosis, cardiac remodeling and endothelial dysfunction, further exploration of the association between these two biomarkers presents an intriguing and worthwhile avenue for extensive research." (PMID 37443671, 2023). "Another study shows that GDF-15 causes endothelial dysfunction by impairing vascular contraction and relaxation." (PMID 34571994, 2021). "It has been reported that an increase in GDF-15 levels in community-based patients is associated with endothelial dysfunction and subclinical cardiovascular disease." (PMID 31581569, 2019). "Thus increased GDF-15 is linked to oxidative stress, inflammation, and endothelial dysfunction." (PMID 26273671, 2015). "Based on the current data available, GDF-15 appears to more likely be an integrative stress biomarker, capturing the influence of inflammation, metabolic dysregulation, endothelial dysfunction, and renal dysfunction." (PMID 41597417, 2026). "Although pathogenic mechanisms differ from typical cardiometabolic disease, oxidative stress leads to endothelial dysfunction and vascular inflammation, stimulating GDF-15 expression." (PMID 41597417, 2026). "In contrast, chronic inflammation primarily triggers for GDF-15 expression in psoriasis, and immunosuppression contributes in rheumatoid arthritis, leading to endothelial dysfunction and pro-atherogenic processes." (PMID 41597417, 2026). "GDF-15 induces endothelial dysfunction by impairing nitric oxide synthesis and promoting endothelial cell apoptosis, which contributes to the initiation and progression of atherosclerotic lesions." (PMID 37888100, 2023). "It seems that survivin can interfere with the elongation of autophagosomes in ECs and prevent excessive autophagy, apoptosis and/or senescence following endothelial dysfunction in GDF-15−/−/ApoE−/− mice after 20 weeks CED." (PMID 34571994, 2021). "Increased circulating levels of GDF-15 have been attributed, inter alia, to endothelial dysfunction." (PMID 33790859, 2021). "Furthermore, GDF-15 is involved in the development of endothelial dysfunction by disrupting the normal functioning of NO-dependent vascular systems and promoting excessive proliferation of endothelial cells, those pathways being commonly shared with the ET-1." (PMID 37443671, 2023). "Indeed, GDF-15 leads to endothelial dysfunction by reducing vascular contraction and relaxation, which ultimately leads to an impaired cardiac function." (PMID 35600479, 2022). "Several reports have shown an association of GDF-15 with all-cause mortality, subclinical cardiovascular disease, endothelial dysfunction, and LV hypertrophy independent of conventional risk factors." (PMID 36001499, 2022). "Likewise, GDF-15 induces endothelial dysfunction not only through its interference with the normal functioning of NO-dependent vascular systems but also by the exaggerated proliferation of endothelial cells." (PMID 36556311, 2022). "Moreover, GDF-15 can lead to endothelial dysfunction through activation of reactive oxygen species pathway." (PMID 34394348, 2021).
endothelial dysfunction (continued). "Endothelial dysfunction in lesion-prone regions of the arterial vasculature is well established to contribute considerably to the pathobiology of atherosclerotic cardiovascular disease, and GDF-15 has been found to be abundant in atherosclerotic plaques in CVD patients." (PMID 38203404, 2023). "Furthermore, it was reported that endothelial dysfunction promotes a higher expression of GDF-15." (PMID 35956112, 2022). "It is reasonable to assume that the association between increased biological markers suggestive of organ dysfunction and the high levels of GDF-15 may actually be based on the severe endothelial dysfunction induced by GDF-15, with a direct impact on coronary, renal, and hepatic microcirculation." (PMID 36556311, 2022). "We identified inflammatory and endothelial dysfunction markers (ADAMTS-13, TNF-α, GDF-15, MIP-1β, VEGFA, MPO, and MIC-1) that cooperate in a common pathway and are increased in FD patients’ plasma samples." (PMID 38892211, 2024). "GDF-15 is an inflammatory and oxidative stress biomarker and recent research suggests a possible role of GDF-15 in myocardial fibrosis, hypertrophy and endothelial dysfunction." (PMID 35892913, 2022). "Notwithstanding the correlation of suPAR and GDF-15 levels with endothelial dysfunction in several clinical entities, these biomarkers have never been studied in patients with HSCT-TMA and GVHD." (PMID 38203404, 2023). "Since endothelial dysfunction plays an important role in the pathogenesis of the COVID-19 infection given that endothelial cells constitute a direct target of SARS-CoV-2, GDF-15 is secreted from the endothelial cells as a direct result of inflammation and oxidative stress produced by the disease." (PMID 35956112, 2022). "GDF-15 is a multifunctional cytokine that belongs to the TGF-beta superfamily and is involved in senescence and modulation of adverse cardiac remodeling, myocardial fibrosis and endothelial dysfunction by suppressing the inflammatory response and potentiating tissue repair." (PMID 35455719, 2022).
gastric cancer (35 papers, 2012 to 2026). A primary or metastatic malignant neoplasm involving the stomach. "Here, we investigated the association between LIF in regulating GDF15 expression and its relationship with metabolic, inflammatory, and body composition alterations in gastric cancer." (PMID 41744798, 2026). "Collectively, these findings identify the LIF/GDF15 axis as a central driver of cancer-associated cachexia in gastric cancer and highlight LIF signaling as a potential therapeutic target." (PMID 41744798, 2026). "Kaplan–Meier analysis showed a significant association between GDF15 levels and poor survival outcomes in gastric cancer patients in the CNUH and GEPIA datasets." (PMID 36769245, 2023). "In the univariate analysis, age (p = 0.001), invasion depth (p < 0.001), nodal involvement (p = 0.005), stage (p < 0.001), tumor size (p < 0.001), and GDF15 expression (p = 0.006) were significant risk factors affecting survival in gastric cancer patients." (PMID 36769245, 2023). "Taken together, our results indicate that GDF15 expression is associated with aggressive gastric cancer by promoting STAT3 phosphorylation, suggesting that the GDF15-STAT3 signaling axis is a potential therapeutic target against gastric cancer progression." (PMID 36769245, 2023). "It was recently suggested that growth differentiation factor‐15 (GDF‐15) is associated with gastric cancer (GC) carcinogenesis." (PMID 30652072, 2019). "In gastric cancer (GC), serum GDF15 levels exhibit diagnostic and prognostic value." (PMID 40868185, 2025). "The data suggested that GDF15 expression is associated with STAT3 expression in gastric cancer." (PMID 36769245, 2023). "However, some studies found that GDF15 expression was up-regulated in gastric cancer patients and its expression was strongly associated with cancer metastasis and invasiveness." (PMID 29262584, 2017). "It is tempting to speculate that up-regulated serum GDF15 may also be involved in gastric cancer related anorexia and weight loss." (PMID 26892343, 2016). "GDF15 might be a promising target for clinical treatment of gastric cancer with CXXC4 deficiency." (PMID 29262584, 2017). "Conversely, GDF-15 overproduction by gastric cancer cells mediates GFRAL signalling in tumour cells, resulting in cisplatin resistance." (PMID 41294666, 2025). "GDF-15 knockdown was shown to promote erastin-induced ferroptosis in human gastric cancer cell line MGC803." (PMID 38743322, 2025). "In the liver metastasis model, we successfully observed GDF15 + SPP1 + TAMs and significantly inhibited the liver metastasis ability of gastric cancer after using GDF15 blockade." (PMID 38365757, 2024). "To further analyze the inhibitory effect of GDF15 on T cells in gastric cancer, we used multigroup gastric cancer BULK datasets." (PMID 38365757, 2024). "We further analyzed the inhibitory effect of GDF15 on T cells in gastric cancer using multiple gastric cancer BULK datasets." (PMID 38365757, 2024). "Next, to further verify the immunosuppressive effect produced by GDF15, we used a GDF15 inhibitor in gastric cancer liver metastasis model mice." (PMID 38365757, 2024). "The expression of GDF15 mRNA was also validated in normal gastric tissues and gastric cancer tissues by RT-qPCR." (PMID 36769245, 2023). "We investigated the function of GDF15 in gastric cancer progression and evaluated GDF15 expression in tumor specimens from 178 patients with gastric cancer." (PMID 36769245, 2023). "Immunohistochemical staining was performed to estimate the expression of GDF15 in 178 gastric cancer tissues." (PMID 36769245, 2023). "To evaluate the role of GDF15 in the proliferation, migration, and invasion of gastric cancer cells, we established GDF15-overexpressing cell lines." (PMID 36769245, 2023). "Although our data has a limitation of the lack of in vivo models, clinical data and in vitro studies strongly suggest that GDF15 promotes the progression of gastric cancer." (PMID 36769245, 2023).
gastric cancer (continued). "Future studies are needed to characterize in vivo function of GDF15 in tumorigenesis of gastric cancer." (PMID 36769245, 2023). "In this study, we investigated the biological function of GDF15 and its effect in gastric cancer progression." (PMID 36769245, 2023). "We investigated that the expression of GDF15 in the GEPIA data set was significantly upregulated in the gastric cancer group compared to the normal group." (PMID 36769245, 2023). "We discovered that the high expression of GDF15 was related to gastric cancer progression and elevated serum GDF15 levels in gastric cancer patients." (PMID 36769245, 2023). "In our results, we found that GDF15 inhibition induced cell cycle arrest in gastric cancer cells by inhibiting STAT3 activation." (PMID 36769245, 2023). "GDF15 overexpression increased cell proliferation and colony formation in gastric cancer cells compared to that in mock cells." (PMID 36769245, 2023). "This suggests that GDF15 can act as a biomarker or predictor of therapeutic resistance to gastric cancer." (PMID 36769245, 2023). "The expression of GDF15 was observed in the cytoplasm of gastric cancer cells and normal gastric mucosal cells." (PMID 34149933, 2021). "In gastric cancer, GDF-15 can be used as a biomarker for gastric cancer; In liver cancer, YTHDF1 expression is elevated in liver cancer patients; In UCEC, Li found that Mammaglobin B is a prognostic marker of UCEC." (PMID 34670872, 2021). "In recent years, numerous studies have been carried out to evaluate the expression level and the role of GDF15 in the biology of many types of human cancers, including gastric cancer." (PMID 34149933, 2021). "In ErbB2-overexpressing gastric cancer cells, GDF-15 was found capable of transactivating EGFR family tyrosine kinases leading to Akt and ERK-1/2 phosphorylation and enhanced invasion." (PMID 32508832, 2020). "In summary, the nuclear protein CXXC4 activated apoptosis in gastric cancer through up-regulating its novel potential downstream target GDF15." (PMID 29262584, 2017). "In the present study, we found CXXC4 activated the transcription of GDF15 to induce apoptosis in gastric cancer." (PMID 29262584, 2017). "As CXXC4 functioned to be a tumor suppressor and GDF15 was a novel CXXC4 downstream target, we further explored the potential tumor suppressing function of GDF15 in gastric cancer." (PMID 29262584, 2017). "Nonetheless, our studies clarified a new signaling pathway of CXXC4/GDF15-induced apoptosis in gastric cancer." (PMID 29262584, 2017). "In contrast, the aberrant increase of secreted GDF15 in serum correlated with poor prognosis in several cancers such as prostate cancer, breast cancer and gastric cancer." (PMID 29262584, 2017). "In summary, CXXC4 stimulated GDF15 transcription via enhancing Sp1 binding to activate apoptosis in human gastric cancer." (PMID 29262584, 2017). "Given the results of our present study, it is likely that CXXC4 was a positive regulator of GDF15 and GDF15 also functioned as a suppressor of tumor progression by inducing cell apoptosis in human gastric cancer." (PMID 29262584, 2017). "Immunoblotting of the six gastric cancer cell lines showed higher GDF15 protein expression of DGC cell lines (KATO-III, OCUM-1, NUGC-4, and MKN-45) than that of IGC cell lines (MKN-7 and MKN-74)." (PMID 26892343, 2016). "The contribution of GDF-15 to the invasiveness of cancer cells has also been described in the context of gastric cancer cells." (PMID 26741507, 2016). "For example, enforced MIC-1/GDF15 overexpression or treatment with purified recombinant MIC-1/GDF15 significantly increased the in vitro invasion of gastric cancer cell lines." (PMID 22952779, 2012). "Consequently, it is important to study the role of GDF15 to identify potential therapeutic targets that can inhibit tumor progression in gastric cancer cells." (PMID 36769245, 2023). "GDF15 knockdown significantly decreases migration and invasiveness in gastric cancer cells." (PMID 36769245, 2023).